RN7SKP158 (RN7SK pseudogene 158)
Gene: Miscellaneous RNA gene on chromosome 11 (28,261,194 to 28,261,519, reverse strand). Ensembl gene ENSG00000222385.
Homologues: Orthologues: chimpanzee 7SK (99% identical). Paralogues in human: RN7SKP192 (67% identical), RN7SKP203 (67% identical), RN7SKP217 (67% identical), RN7SKP170 (66% identical), RN7SKP176 (66% identical), RN7SKP180 (66% identical), RN7SKP246 (66% identical), RN7SKP33 (66% identical), RN7SKP79 (66% identical), RN7SKP86 (66% identical), 7SK (65% identical), RN7SKP211 (65% identical), and 284 more.